IGFBP2 (insulin like growth factor binding protein 2)
Diseases named in the same sentence as IGFBP2 in open-access papers (continued):
Sharing a sentence is not in itself a finding about the gene and the disease.
Brain atrophy (7 papers, 2013 to 2025). Partial or complete wasting (loss) of brain tissue that was once present. "CSF and plasma IGFBP-2 levels are elevated in AD, and plasma levels of IGFBP-2 are associated with smaller hippocampal volumes and brain atrophy." (PMID 37175824, 2023). "Plasma macrophage inhibitory protein-1α and insulin-like growth factor binding protein 2 showed a significant association with brain atrophy in the adjusted model." (PMID 23408997, 2013). "Insulin-like growth factor binding protein-2 (IGFBP-2) is associated with AD and brain atrophy." (PMID 36185474, 2022). "Higher IGFBP-2 levels were associated with increased brain atrophy." (PMID 23408997, 2013). "AD patients have elevated levels of plasma and CSF IGFBP-2 compare to normal old individuals and plasma IGFBP-2 associated with AD-like brain atrophy." (PMID 31824433, 2019). "In this study, we found an association between AD-like patterns of brain atrophy, quantified by the SPARE-AD index, and plasma cortisol, CgA, IGFBP-2 and MIP-1α levels." (PMID 23408997, 2013). "As impaired IGF signaling contributes to tau dysregulation, the effect of IGFBP-2 on IGF signaling may explain how IGFBP-2 contributes to tau-related brain atrophy." (PMID 30061810, 2018). "CSF IGFBP-2 levels were correlated with CSF tau levels and brain atrophy in non-hippocampal regions." (PMID 30061810, 2018). "In a recent study examining the relationship between AD and IGFBP2 levels across a spectrum of 300 human AD patients and two transgenic mouse models of AD, investigators found cerebrospinal fluid (CSF) IGFBP2 levels correlated with CSF tau levels and brain atrophy in non-hippocampal regions." (PMID 32226608, 2020).
brain tumor (7 papers, 2010 to 2023). "IGFBP-2 alone cannot cause malignant transformation, yet progression of brain tumors to higher grade and also has been provided as a protective element in earlier stages of multistage colon carcinogenesis." (PMID 24778626, 2014). "LEM treatment of the GL261 brain tumor greatly reduced the expression of Pdgfd, Pdgfra and Igfbp2, as detected by quantitative RT-PCR, compared to vehicle control tumors." (PMID 34470658, 2021). "For example, increased levels of IGFBP-2 are found in rapidly growing non-invasive brain tumours, whereas low/undetectable levels are observed in malignant invasive brain tumours." (PMID 31903164, 2019). "Interestingly, this is also supported by an in vivo model of malignant brain tumor growth and invasion, where rapidly growing non-invasive tumors have high levels of IGFBP2 compared to invasive tumors, which had low/undetectable IGFBP2 levels." (PMID 25774149, 2015). "Our current study, which focused exclusively on grade 4 diffuse gliomas, the most aggressive primary brain tumors, revealed that a nomogram based on COL22A1, IGFBP2, and MPO expression can reliably evaluate patient prognosis." (PMID 37737709, 2023).
cervical cancer (7 papers, 2015 to 2025). A primary or metastatic malignant neoplasm involving the cervix. "The results suggest that the IGF/IGFR/IGFBP2 axis would make a logical target for further investigation for potential treatment of cervical cancers." (PMID 26107517, 2015). "Our in vitro findings are mirrored in cervical cancer specimens where IGFBP2 expression is commonly lost in 85% of CIN3 lesions, which progress to invasive disease with high incidence, if left untreated, while CIN1 lesions do not." (PMID 26107517, 2015). "This was also established in a modified organotypic raft culture containing the HPV16 positive cervical cancer cell line, Caski, where IGFBP2, but not IGFBP3, significantly inhibited invasion of the epithelial cells." (PMID 26107517, 2015). "There is also a correlation between IGFBP2 levels and HPV in publicly available microarray datasets from various cervical cancer cell lines where HPV positive cervical cancer cell lines were shown to have substantially reduced IGFBP2 expression compared to HPV negative cervical cell lines." (PMID 26107517, 2015).
Cognitive impairment (7 papers, 2020 to 2026). Abnormal cognition is characterized by deficits in thinking, reasoning, or remembering. "Remarkably, the local infusion of recombinant Igfbp2 protein restored synaptic architecture and rescued cognitive deficits." (PMID 42058900, 2026). "First, while our study identified Igfbp2 as a key mediator in anesthesia‐induced cognitive impairment, the specific signaling pathways and molecular mechanisms through which Igfbp2 affected neuronal excitability and synaptic function warrant further research." (PMID 40801458, 2025). "Our findings provide a new insight into the mechanisms of anesthesia‐induced cognitive impairment and highlight Igfbp2 as a potential therapeutic target." (PMID 40801458, 2025). "In conclusion, our findings demonstrate that Igfbp2 in the PVT glutamatergic neurons projecting to the CeA plays a crucial role in mediating anesthesia‐induced long‐term cognitive impairment in mice of both sexes." (PMID 40801458, 2025). "The findings demonstrate that Igfbp2 in glutamatergic neurons in the PVT afferents to the CeA mediates fear memory deficits caused by repeated neonatal anesthesia in mice of both sexes, highlighting Igfbp2 as a potential therapeutic target for repeated anesthesia‐induced cognitive impairment." (PMID 40801458, 2025).
COVID-19 (7 papers, 2022 to 2025). A disease caused by infection with severe acute respiratory syndrome coronavirus 2. "In the current study, we demonstrated that reduced IGFBP2 expression represents a novel pathogenic mechanism for alveolar epithelial cell inflammation in the pathogenesis of COVID-19." (PMID 40121473, 2025). "The present analysis showed that higher serum IGFBP-2 levels are associated with increased disease severity in COVID-19 patients." (PMID 38255230, 2024). "Higher serum IGFBP-2 levels are associated with increased disease severity and lower survival rates in COVID-19 patients." (PMID 38255230, 2024). "In the context of COVID-19, studies have found a clear association between elevated serum IGFBP-2 levels and fatal outcomes in hospitalized patients." (PMID 39585162, 2024). "The aim of this study was to analyze the associations of serum IGFBP-2 levels with COVID-19 severity, and therefore, serum IGFBP-2 levels were determined in healthy controls and patients with moderate and severe COVID-19 disease." (PMID 38255230, 2024). "In severe COVID-19 cases, positive associations were found between serum IGFBP-2 and procalcitonin, AP, and ferritin." (PMID 38255230, 2024). "We found that serum IGFBP-2 levels were higher in severe COVID-19 patients compared to both healthy controls and those with moderate disease, suggesting a relationship with disease severity." (PMID 38255230, 2024). "This observational study cannot identify the mechanisms contributing to higher serum IGFBP-2 in severe COVID-19." (PMID 38255230, 2024). "IGFBP-2 levels in COVID-19 patients have been described in one study, and plasma IGFBP-2 was found to be elevated in hospitalized COVID-19 patients compared to healthy controls in a proteomic analysis." (PMID 38255230, 2024). "Patients with both moderate and severe COVID-19, who required dialysis, exhibited increased serum IGFBP-2 levels." (PMID 38255230, 2024). "Previous studies have reported increased serum IGFBP-2 levels in critical illness, and higher IGFBP-2 levels in severe COVID-19 are consistent with these findings." (PMID 38255230, 2024). "The similarity in serum IGFBP-2 levels between patients with moderate COVID-19 and healthy controls suggests that elevated IGFBP-2 is associated with critical illness rather than SARS-CoV-2 infection itself." (PMID 38255230, 2024). "Here, we measured the serum IGFBP-2 levels of COVID-19 patients with moderate and severe disease as well as healthy controls to identify the associations of serum IGFBP-2 levels with disease severity." (PMID 38255230, 2024). "The 57 moderate COVID-19 patients exhibited IGFBP-2 levels similar to those of the 60 severe patients and 23 healthy controls (p = 0.140)." (PMID 38255230, 2024). "Patients with severe COVID-19 had higher serum IGFBP-2 levels than those with moderate disease and healthy controls, who had similar levels." (PMID 38255230, 2024). "IGF1 was found to be low in the serum of patients with severe COVID-19, and the present analysis showed that this is in parallel with a rise in serum IGFBP-2 levels." (PMID 38255230, 2024). "In moderate COVID-19 patients, IGFBP-2 levels were positively correlated with CRP, procalcitonin, LDH, AP, and IL-6, and negatively correlated with lymphocyte count." (PMID 38255230, 2024). "The plasma IGFBP-2 levels of COVID-19 patients were higher in contrast to the healthy controls (p < 0.001) (AUROC 0.879; p < 0.001; 95% CI 0.773–0.985)." (PMID 38137505, 2023). "Previous studies have associated IGFBP-2, IGF1 with adverse outcomes in COVID-19 patients." (PMID 39802657, 2024). "The similarity in serum IGFBP-2 levels between patients with moderate COVID-19 and healthy controls indicates that elevated IGFBP-2 is linked to critical illness rather than SARS-CoV-2 infection itself." (PMID 38255230, 2024). "Interestingly, IGFBP-2 was shown to discriminate patients with COVID-19 from healthy subjects, serving as controls." (PMID 39585162, 2024).
COVID-19 (continued). "This study shows that serum IGFBP-2 is a prognostic factor for COVID-19 severity." (PMID 38255230, 2024). "Furthermore, the rise in IGFBP-2 during CI may reflect an adaptive response to the cytokine storm, common in severe infections and septic conditions, including those seen in COVID-19." (PMID 39585162, 2024). "However, the serum IGFBP-2 levels of male and female patients with COVID-19 were similar." (PMID 38255230, 2024). "Given the association of lymphopenia with COVID-19 severity and higher mortality, particularly in moderate and severe cases, the negative correlation of IGFBP-2 with lymphocyte count in moderate COVID-19 may indicate its association with disease severity." (PMID 38255230, 2024). "Thus, higher circulating levels of IGFBP-2 are related to mortality in the general population, in patients with cardiovascular diseases, and, according to our study, in patients with COVID-19." (PMID 38255230, 2024). "Therefore, elevated systemic IGFBP-2 is a marker of severe illness and may be useful in monitoring disease severity and guiding therapy in COVID-19 patients." (PMID 38255230, 2024). "Notably, COVID-19 patients also had elevated IGFBP-2 plasma levels compared to controls." (PMID 38137505, 2023). "In this study, we have uncovered a critical role for IGFBP2, specifically in alveolar epithelial type 2 cells (AEC2), in the immunopathogenesis of COVID-19." (PMID 40121473, 2025). "Future studies are required to determine how IGFBP2 inhibits cytokines—TNF-α and IL6—and chemokine—CCR5, are critical for improving COVID-19 outcomes." (PMID 40121473, 2025). "Together, these results indicate reduced expression of IGFBP2 and its selective ligands IGF1 and IGF2 specifically in AEC2 cells from patients diagnosed with severe or moderate COVID-19." (PMID 40121473, 2025). "Liver cirrhosis and adiposity affect serum levels of IGFBP-2, and the exclusion of these patients showed that the serum IGFBP-2 levels of patients with severe COVID-19 were higher in comparison to those of patients with moderate disease and healthy controls." (PMID 38255230, 2024). "Altogether, these data suggest that anti-inflammatory properties of IGFBP2 in AEC2 cells and its localized delivery may serve as potential therapeutic strategy for patients with COVID-19." (PMID 40121473, 2025). "Using bulk RNA sequencing and multicolor-immunohistochemistry, we demonstrated that IGFBP2 was significantly reduced in AEC2 cells from patients with COVID-ARDS, IPF alone, or IPF with a history of COVID-19 (IPF with COVID history) compared with healthy donor controls." (PMID 40121473, 2025). "The time from the onset of COVID-19 symptoms to clinical cure ranges from 8 to 53 days, with large inter-individual variability, and IGFBP-2, CRP, procalcitonin, and IL-6 were not related to the time of blood collection in our cohort." (PMID 38255230, 2024). "In patients with COVID-19, elevated IGFBP-2 levels have been measured, particularly in non-survivors." (PMID 39585162, 2024). "While IL-6 and ferritin are proposed markers for COVID-19, they did not correlate with the plasma IGFBP-2 levels in our COVID-19 subgroup." (PMID 38137505, 2023). "While IL-6 and ferritin are indicators of COVID-19 severity, they did not correlate with plasma IGFBP-2." (PMID 38137505, 2023). "Pneumonia, especially prevalent in COVID-19 patients, did not correlate with changes in plasma IGFBP-2." (PMID 38137505, 2023). "Collectively, these findings suggest that IGFBP2 is downregulated in AEC2 cells and its targeted expression may regulate SARS-CoV-2-induced inflammation, and therefore yield therapeutic options for patients with COVID-19." (PMID 40121473, 2025). "Obese COVID-19 patients had lower levels of IGFBP-2 than non-obese patients." (PMID 38255230, 2024). "Bacterial co-infection in severe COVID-19 patients did not influence serum IGFBP-2 levels." (PMID 38255230, 2024).
COVID-19 (continued). "Non-survivors of COVID-19 tended to have elevated serum IGFBP-2 levels compared to survivors." (PMID 38255230, 2024). "However, the relationship between IGFBP-2 and COVID-19 is complex, as obese COVID-19 patients tend to exhibit lower IGFBP-2 levels compared to non-obese patients, necessitating further investigation into the interplay between metabolic factors and IGFBP-2 expression in different patient populations." (PMID 39585162, 2024).
depression (7 papers, 2011 to 2024). "Specifically, it was found that IGFBP-2 protein serum levels were significantly reduced in BD patients compared not only to matched controls but also other mental conditions such as depression." (PMID 38720780, 2024). "An index of SASP proteins was associated with antidepressant response to late-life depression in a nonrandomized trial of 416 older adult participants with major depressive disorder, but neither GDF-15 nor IGFBP-2 were included for consideration in the development of their SASP index." (PMID 37982669, 2024). "Previous studies have compared the proteomic profiles of depressed patients and healthy controls, finding that in atypical depression, but not melancholic, both IGFBP-1 and IGFBP-2 were significantly decreased." (PMID 37894932, 2023).
squamous cell carcinoma (7 papers, 2012 to 2026). A carcinoma arising from squamous epithelial cells. "Multiple papers have demonstrated that higher levels of IGFBP-2 are associated with worse OS in lung adenocarcinoma, squamous cell carcinoma, and small cell carcinoma, and these higher levels are associated with increased rates of metastasis and higher staging." (PMID 35198099, 2022). "However, one of these studies did associate high IGFBP-2 levels with favorable OS in patients with squamous cell carcinoma." (PMID 35198099, 2022). "IGFBP2 is one of the proteins found to be significantly increased in primary tumor tissues of non-small-cell lung cancers, including adenocarcinoma and squamous cell cancer." (PMID 24069370, 2013). "Human squamous cell carcinoma NCI-H520 and murine lung adenoma LA-4 cell lines were transfected with vectors encoding murine Igfbp5 or Igfbp2 and, after selection with blasticidin, were scored for colony formation." (PMID 22973541, 2012). "Increased IGFBP2 and IGFBP5 mRNA levels were correlated with increased overall survival in squamous cell carcinoma patients." (PMID 36465383, 2022). "When expression in different histological types was compared, the expressions of ATM, Ku80, IGFBP2, IRS1-pS307, and S6 were significantly higher in neuroendocrinal carcinoma than in adenocarcinoma or squamous cell carcinoma (p<0.05)." (PMID 22348039, 2012).
Stroke (7 papers, 2010 to 2024). Sudden impairment of blood flow to a part of the brain due to occlusion or rupture of an artery to the brain. "Plasma THBS1 and CFD are confirmed as CHD risk markers, and plasma IGFBP4 and IGFBP2 are confirmed as stroke risk markers." (PMID 24373343, 2013). "These analyses also imply positive associations of stroke risk with IGFBP2, IGFBP4, and B2M." (PMID 24373343, 2013). "However, there was limited evidence of important mediation of HT effects on stroke by either IGFBP4 or IGFBP2, and only a weak suggestion of a positive association between IGFBP4 change from baseline to year 1 and stroke risk." (PMID 24373343, 2013). "Our results suggest a possible beneficial effect of IGFBP-2 blockage in the context of CE stroke modulating endothelial dysfunction." (PMID 38673963, 2024). "Among these, IGFBP-2 stood out not only as a potential circulating biomarker of embolic stroke etiology but also as a regulator of clot formation and lysis and endothelial function." (PMID 38673963, 2024). "Here, our validation exercises confirm a positive association of plasma IGFBP2 and IGFBP4 with stroke risk among postmenopausal women." (PMID 24373343, 2013). "The strongest associations in these analyses are for B2M and CHD and for IGFBP4 and stroke, while an inverse association of CHD risk with THBS1 and a positive association of stroke risk with IGFBP2 are also observed." (PMID 24373343, 2013). "It confirms the previous mRNA data and further demonstrates that the increase changes the distribution pattern of IGFBP-2 in control vs. stroke conditions." (PMID 24359611, 2013). "This work has also led to the identification of plasma B2M, IGFBP2, and especially IGFBP4 as novel risk markers for stroke risk among postmenopausal women." (PMID 24373343, 2013). "Using an enzyme-linked immunosorbent assay (ELISA), we measured IGFBP-2 and IGF-I protein levels in the stroke brain." (PMID 24359611, 2013). "For stroke, positive correlations of B2M with each of IGFBP2, IGFBP4, and IGFBP6 were also evident at baseline and year 1 in both treatment groups, and both trials." (PMID 24373343, 2013). "B2M, THBS1, and CFD were confirmed (P <0.05) as novel CHD risk markers, and B2M, IGFBP2, and IGFBP4 were confirmed as novel stroke disease risk markers, while the assay for HPX proved to be unreliable." (PMID 24373343, 2013). "However, circulating levels of IGFBP-2 were similarly increased in CE stroke, consistent with the observation of EVs in the RNASeq analysis and significantly associated with IS etiology in the multivariate analysis." (PMID 38673963, 2024). "Fifth, P2Y1R and IGFBP2 were upregulated in models of both seizure and stroke." (PMID 39117630, 2024). "Interestingly, the levels of IGFBP-2 in hypertensive patients with concomitant AF, were similar to the IGFBP-2 levels in CE stroke patients." (PMID 38673963, 2024). "However, 72 h post-stroke, IGFBP-2 levels significantly increased in the stroke penumbra (5-fold) and core (3-fold) when compared to the contralateral hemisphere." (PMID 24359611, 2013). "In the current study we chose to explore IGFBP-2 expression and distribution in the brain in the chronic phases of stroke, which would help elucidate if there is potential for further protection/repair of the neuron population and remodeling of the penumbra and core." (PMID 24359611, 2013). "In addition, we show using the transient middle cerebral artery occlusion (MCAO) model in mice that there is a significant increase in IGFBP-2 levels in the stroke penumbra and core after 72 h." (PMID 24359611, 2013). "Similarly, IGF-I independent role of IGFBP-2 after stroke, needs to be further investigated using IGFBP-2 inhibition experiments." (PMID 24359611, 2013). "Also, it is interesting that four of the eleven top-ranked proteins for association with stroke risk are members of the IGF signaling pathway (IGFBP4, IGF2, IGFBP6, IGFBP2)." (PMID 20667078, 2010).